MITF (melanocyte inducing transcription factor)
Diseases named in the same sentence as MITF in open-access papers (continued):
Sharing a sentence is not in itself a finding about the gene and the disease.
melanoma (continued). "When BRAF-MEK inhibition occurs, MITF suppression is relieved, allowing elevated levels of MITF to promote PGC1α-mediated mitochondrial biogenesis and OXPHOS in melanoma." (PMID 39501277, 2024). "The MC extract also decreased the expression of MITF, CDK2, c-Met, Bcl2, and RAB27A, which had increased with melanoma cell treatment." (PMID 39684511, 2024). "We then assessed the effect of MITF silencing on miR-579-3p, ZFR and TYR expression levels in three different melanoma cell lines (i.e. LOX IMVI, WM266 and M14)." (PMID 38472212, 2024). "MC extract administration induced the amelioration of melanoma by controlling the PAX3/PTEM/PIP3/Akt/mTORC1 and PAX3/MITF/CDK2·c-Met·Bcl2·RAB27A signaling pathways, which are involved in melanoma proliferation and invasion." (PMID 39684511, 2024). "Tirosh and colleagues defined proliferative (MITF program), invasive (AXL program), and resistant (Tirosh “Resistance” program) melanoma cell states using single-cell RNAseq (scRNAseq) data from patients." (PMID 39709491, 2024). "Luciferase results demonstrated that MITF silencing reduces the activation levels of miR-579/ZFR promoter as compared to SCR in LOX IMVI and WM266 melanoma cells." (PMID 38472212, 2024). "According to recent studies, MITF is required for melanin synthesis, but MITF is unable to induce the expression of tyrosinase and TYRP1 in B16 mouse melanoma cells or human melanocytes." (PMID 38711645, 2024). "As further evidence that components of the GSK3β/MITF axis are affected by Rab7a/TPC2 activity, we demonstrated that β-Catenin is reduced in Rab7a as well as in TPC2 KO melanoma lines." (PMID 39562548, 2024). "MITF, a pivotal regulatory element in melanocyte development and differentiation, plays a facilitating role in EMT within the extracellular matrix of melanoma cells." (PMID 38683136, 2024). "We have previously reported that genetic knockdown (KD) of the transcriptional coactivator p300 in melanoma cells results in significantly lower expression of SOX10 and MITF proteins." (PMID 38994683, 2024). "Mining of a SOX10 KD dataset identified MITF, SCD, and MYC as being downstream SOX10 effector genes in this melanoma phenotype." (PMID 38994683, 2024). "Of relevance, the microscopic analysis of the corresponding xenotransplants allowed the identification of clusters of MITF-/CDH1-/CDH2 + /ZEB1 + /CD271 + cells, supporting the existence of melanoma-initiating cells also in MM, as confirmed in clinical samples." (PMID 38191367, 2024). "Therefore, inhibitors of PAX3/MITF expression may sensitize melanomas to BRAF/MEK inhibitors." (PMID 38473380, 2024). "The obtained results showed that tigecycline decreased the levels of MITF and p44/42 MAPK proteins in both tested melanoma cell lines." (PMID 37371034, 2023). "Thus, unidentified MITF target genes may represent new molecular targets for melanoma therapy." (PMID 37658191, 2023). "In melanoma cells, MITF and TFEB participate in cross-regulatory circuits, in which MITF enhances the expression of TFEB, while TFEB inhibits MITF expression." (PMID 37160873, 2023). "Uveal melanoma-specific hits were enriched for YREs present in the loci of three master regulators of gene expression in the melanocytic lineage and melanoma: PAX3, SOX10 and MITF." (PMID 37400441, 2023). "MITF and GREB1 were strongly co-expressed in approximately 8/20 (40 %) of nevi and 17/89 (20%) of melanoma cases." (PMID 37658191, 2023). "MITF and GREB1 Is4 were strongly co-expressed in approximately 20% of the melanoma specimens evaluated (17/89 cases) and their expression was associated with tumor thickness." (PMID 37658191, 2023).
melanoma (continued). "For instance, SAMMSON is co-induced with the melanoma-specific oncogene MITF, and it is highly expressed in most melanomas, while knock-down of SAMMSON decreases melanoma cell viability and sensitizes melanoma to therapeutics." (PMID 36869839, 2023). "These AXL-high MITF-low cells were admixed with AXL-low MITF-high differentiated cells, demonstrating cellular heterogeneity present in untreated melanomas." (PMID 37021774, 2023). "Given the loss of pigmentation and low levels of nuclear MITF, as well as the increase in metastatic and invasive markers that characterize the TG2 KO clones, we speculated that TG2 could play a role in regulating the transition between melanoma plasticity signatures." (PMID 37898636, 2023). "In melanoma, the protective effect of finasteride on melanogenesis via downregulation of tyrosinase, TRP-1, MITF, and ACs expression has been demonstrated, further in vivo animal experiments are required for confirmation." (PMID 37993971, 2023). "Several oncogenes such as melanocyte inducing transcription factor (MITF) and SAMMSON exist in this amplicon that has a pivotal function in melanoma genesis." (PMID 37772815, 2023). "MITF pathway inhibitor ML329 has been reported to inhibit cell survival and proliferation in melanoma." (PMID 36834926, 2023). "6-methylcoumarin can increase the MITF and tyrosinase expression in B16F10 melanoma cells by inducing AKT phosphorylation." (PMID 37299026, 2023). "MITF downregulation is also obtained after ML329, an inhibitor of the MITF pathway in melanoma treatment, reinforcing the whole data." (PMID 36834926, 2023). "In melanoma patients, the signal transducer and activator of transcription 3 (STAT3), which is known to antagonize MITF expression, has been found to play a role in melanoma ICD." (PMID 37626741, 2023). "Interestingly, the fraction of A375P cells showing low MITF expression was significantly higher in cells disconnected from tumor masses, suggesting a dynamic regulation of MITF expression depending on the proliferative (tumor masses) versus invasive (migrating cells) states of melanoma cells." (PMID 36692026, 2023). "Another mechanism suggesting melanoma progression includes altering the miRNA-539-3p/USP13 signaling to reduce de-ubiquitination of MITF protein, increasing MITF degradation, and allowing further invasion." (PMID 36833272, 2023). "While differentiated melanoma cells exhibit high levels of MITF and SOX10, dedifferentiated melanoma cells show low expression of MITF and high expression of mesenchymal markers." (PMID 37370757, 2023). "In the serial sections of melanoma tissues expressing high GREB1 and MITF, the staining intensity for GREB1 and MITF was quantified and classified into four categories with pseudo-color." (PMID 37658191, 2023). "This miRNA has been found to suppress the expression of cMYC, Y-box binding protein 1 (YB1), MITF and EZH2 in melanoma." (PMID 37325482, 2023). "And also, MITF and GALNT16 were significantly enriched in the KEGG pathway of melanoma and mucin type O-glycan biosynthesis, respectively." (PMID 36707771, 2023). "The noted decreases in MITF and p44/42 MAPK in individual melanoma cell lines also reflect the greater sensitivity of COLO 829 cells to the action of tigecycline, as demonstrated in other analyses." (PMID 37371034, 2023). "Taken together, our study helps elucidate the molecular details of how MITF interacts with CBP/p300 through multiple redundant interactions that lend insight into MITF function in melanocytes and melanoma." (PMID 37752231, 2023).
melanoma (continued). "In single-cell analysis of human melanomas, a subpopulation of cells expressing high levels of AXL, a putative cancer stem cell marker, and low levels of MITF were present in treatment-naive human melanoma samples." (PMID 37021774, 2023). "These ‘nevi and melanoma’ genes include BRAF, CDKN2A, MITF, some telomere length maintenance genes, and IRF4." (PMID 36834954, 2023). "Additionally, other biomarkers such as MITF (microphthalmia-associated transcription factor), IDO (indoleamine 2,3-dioxygenase), and MDM2 (mouse double minute 2 homolog) have shown promise in regulating melanoma cell behavior, offering potential avenues for targeted therapeutic strategies." (PMID 37629523, 2023). "In the resected primary melanoma tumors, high expression of GREB1 (scores = 2 and 3) and MITF (score = 3) were observed in 30/89 (33.7%) and 34/89 (38.2%) tumors, respectively." (PMID 37658191, 2023). "In order to evaluate the phenotypic diversity of our samples, we mapped the expression profile of key melanoma cell-state regulatory genes such as the NGFR, RXRG, MITF, SOX10, SOX9 and AXL genes." (PMID 36765773, 2023). "Although melanoma can be classified into MITF-low/AXL-high or MITF-high/AXL-low melanoma at the tumor level, subclones with AXL-high and MITF-high expression co-exist in melanoma at the single cell level." (PMID 37239381, 2023). "The study of NNMT, PON2, Nrf2, MITF, IDO, and MDM2 as potential biomarkers in melanoma holds great promise for improving diagnosis and advancing targeted therapies." (PMID 37629523, 2023). "MITF binds the CLEAR-box element in the promoters of lysosomal and autophagosomal genes in melanoma cells and melanocytes." (PMID 37123908, 2023). "It has been demonstrated that enhancer signatures are strongly enriched for SOX10/MITF and AP-1/TEAD regulome in melanoma." (PMID 37904237, 2023). "For example, MITF and AXL are recurring and show similarities to the “phenotype switching model” characterized by the ability of melanoma cells to adapt to their microenvironment." (PMID 37762707, 2023). "The polyphenol-enriched Rosa rugosa extract exerts similar effect as observed in the current study by reducing the mRNA and protein expression levels of MITF, tyrosinase, TRP-1, and TRP-2 in murine melanoma cells." (PMID 37511600, 2023). "It has been reported that there are mainly three types of melanoma, including melanocytic (proliferative), mesenchymal-like (invasive), and neural crest stem cell (NCSC)-like, depending on MITF-regulated transcriptional states." (PMID 37658191, 2023). "Another potential target to increase melanoma tumor immunogenicity is the transcriptional activator SOX10, which also regulates MITF." (PMID 37626741, 2023). "Acting as a transcription factor, MITF up‐regulates PEDF transcription and expression via binding to PEDF RNA in melanoma cells." (PMID 37070131, 2023). "In this study, we investigated the anti-melanogenic effects of ITA and DMI on α-MSH-induced MITF expression and the modulatory role of AKT and GSK3β in melanogenesis in B16F10 mouse melanoma cells." (PMID 35807430, 2022). "Western blot analysis demonstrated that WFP reverse α-MSH induced melanogenesis in A375 melanoma cells, including in down-regulated TRY, TYRP-1, TYRP-2, MITF and CREB expressions." (PMID 35752787, 2022). "Taken together, these results highlight a new level of regulation of MITF by RAF, two key players of melanoma biology." (PMID 35091687, 2022). "Thus, the overexpression of ERK1/2 and MITF, observed in most of the tested samples, may play some positive roles; however, the effect requires further research and should be considered regarding the use of tetracyclines as adjuvant therapy for melanoma." (PMID 35055021, 2022). "A recent report demonstrated that MITF regulates the expression of SOX10, and our RNAseq data shows that SOX10 is also significantly depleted in the TXNRD1+/− melanoma cells (less than 1% that of the TXNRD1wt cells, padj = 1.2 × 10−10)." (PMID 36291795, 2022).
melanoma (continued). "In this study, we have explored how the melanocyte differentiation–specific transcription factors, MITF and SOX10, are epigenetically regulated and determine melanoma aggressiveness, cell phenotype, and therapy response." (PMID 36040798, 2022). "Evidence from in vivo models and human clinical samples has led to a proposed model of phenotype switching during melanoma progression, fine-tuned by ZEB1/2, TWIST1, and SNAIL2, as well as MITF expression." (PMID 35267510, 2022). "TSP-1 levels were also inversely correlated with MITF expression and pigmentation, suggesting the oncogenic role of this factor correlated with de-differentiated EMT-like melanoma phenotypes." (PMID 35565234, 2022). "One current view for the therapeutic strategy is to increase MITF levels and therefore those of melanoma antigens, such as MART-1 and GP-100, to increase the recognition of melanoma cells by T cells and improve the immune response." (PMID 35158973, 2022). "Upstream of MITF, reduced SOX10 expression has been reported throughout melanoma development, from early to metastatic stages." (PMID 36040798, 2022). "One of the most evident up-regulated melanoma specific transcription factors expressed in all melanoma cell lines was SOX10, while several proteins related to melanogenesis were increased only in MITF positive cell lines." (PMID 36776379, 2022). "The MITF and SOX10 transcription factors act as important regulators of melanoma phenotypic-state transition and control invasive and metastatic features of melanoma." (PMID 35159386, 2022). "Overall, the complex interactions between MITF and BRN2 are essential in regulating each other, creating a heterogeneous tumour and in driving melanoma progression." (PMID 35740696, 2022). "TAMs affect melanoma cells by releasing TNF alpha, thereby sustaining survival signaling pathways in melanoma cells by enhancing MITF expression." (PMID 35558554, 2022). "Some important signaling pathways involved in the pathogenesis of melanoma are the mitogen-activated protein kinase (MAPK) pathway, the phosphoinositide 3-kinase (PI3K/PTEN/AKT) pathway, and the MITF signaling pathway." (PMID 35893303, 2022). "Korean scholars found that purple grape root extract birchic acid inhibited melanin synthesis by modulating MEK/ERK and PI3K/Akt pathways to suppress CREB, MITF, and TRP-1/2 expression in B16F10 melanoma cells." (PMID 35770009, 2022). "This study demonstrated the anti-melanogenic activity of calycosin, a common dietary isoflavonoid, by decreasing expressions of MITF and its target genes tyrosinase and TRP-2 in B16F10 melanoma cells." (PMID 35163281, 2022). "In aggressive melanoma tumors, AXL and MITF levels inversely correlate, showing MITFlow/AXLhigh expression characterized by a slow proliferating state, invasion, and metastasis formation." (PMID 35956175, 2022). "Several markers were used including Melan-A/MART1, human melanoma black-45 (HMB-45) antigen, S-100 protein, p16, MiTF, and, relatively recently, the preferentially expressed antigen in melanoma (PRAME)." (PMID 36140597, 2022). "The MITF transcription factor and the RAS/RAF/MEK/ERK pathway are two interconnected main players in melanoma." (PMID 35091687, 2022). "P300 up-regulates MITF gene expression by inducing H3K27ac at the MITF gene promoter, resulting in the up-regulation of MITF target oncogenes, such as FOXM1, and melanoma cell proliferation." (PMID 35836809, 2022). "In the present study, ITMFAb decreased MITF expression and tyrosinase expression in B16BL6 melanoma cells exposed to α-MSH." (PMID 36422527, 2022). "ACLY induces the resistance to MAPK inhibition by activating acetyltransferase P300 to acetylate the histone at the MITF locus, thus promoting the transcription of the MITF-PGC1 α axis and ultimately facilitating melanoma growth." (PMID 36003368, 2022).
melanoma (continued). "Here, we investigated the inhibitory effect of ITA and DMI on alpha-melanocyte-stimulating hormone (α-MSH)-induced MITF expression and the modulatory role of protein kinase B (AKT) and GSK3β in melanogenesis in B16F10 mouse melanoma cells." (PMID 35807430, 2022). "As our data show that DUSP4 depletion leads to cell death through MITF suppression, we evaluated the sensitivity of BRAF/NRAS–mutant melanoma cells expressing either high or low levels of MITF to DUSP4 knockdown." (PMID 35580987, 2022). "For instance, in a human melanoma cell line, the in vitro enhancer activity of an element within an IRF4 intron depended on the simultaneous binding of MITF and TFAP2." (PMID 35580127, 2022). "The anti-melanoma effect of analyzed drugs appeared to be related to the up-regulation of ERK1/2 and MITF." (PMID 35055021, 2022). "In addition, it may alter the motif of POU3F2, a transcription factor (TF) present in melanoma cell lines known to alter the expression of pigmentation genes (i.e. MITF, KITLG), although a recent study suggests that this TF does not have a role in normal skin melanocytes." (PMID 35712076, 2022). "Conclusively, melanoma cells with concurrent MITF and SOX10 promoter methylation are phenotypically different from the MITF-methylated SOX10+ cells." (PMID 36040798, 2022). "An in vivo imaging study on melanoma cell lines has indicated that the BRN2 expression is increased in invasive cells of the primary tumor, while MITF expression is lost." (PMID 36224606, 2022). "Our study demonstrates that in BRAF- and NRAS-mutant MITF-proficient melanoma, the DUSP4 MAPK phosphatase restricts MAPK activation and prevents oncogenic overdose through modulation of MITF function." (PMID 35580987, 2022). "To investigate the potential mechanism by which NUMB regulates invasion in melanoma, we performed quantitative real time-PCR to evaluate the expression of CCNE and MITF in WM1799 and WM3451." (PMID 34883044, 2022). "It was also identified that the antagonism between MITF and c-Jun acts as a molecular interface between pro-inflammatory signals from the TME and melanoma plasticity." (PMID 35406721, 2022). "In a multi-dermatology meta-analysis study, MITF and TRY were also found to be specifically elevated in melanoma." (PMID 35893303, 2022). "It was known that in activated melanoma cells extracellular signaling kinases 1 and 2 (ERK1/2) regulate phosphorylation of MITF on the Serine 73 residue." (PMID 35159398, 2022). "Further in vitro and in vivo studies found that AR increased MITF protein degradation by modulating miRNA‐539‐3p/USP13 signalling, which resulted in increased melanoma cell invasion by increasing the expression of the receptor tyrosine kinase AXL." (PMID 35452181, 2022). "While gross specimens that clearly arise from nerves lend credence to a diagnosis of MPNST, negative staining for cytokeratins and melanoma markers like Melan-A, MITF, and HMB45 can be useful in distinguishing MPNST from carcinoma and melanoma." (PMID 35244537, 2022). "7-MSI treatment significantly reduced melanogenesis in B16F1 melanoma cells via activation of ERK signaling, leading to activation of autophagy and downregulation of MITF, tyrosinase and TRP-1." (PMID 35645796, 2022). "This response corresponded with the largely variable MITF/AXL ratios from the cells, a well-known predictor of resistance in melanoma for which low ratios have been related with a multidrug-resistant phenotype." (PMID 36434616, 2022). "Our data show that both MITF-high and MITF-low BRAF-mutant melanoma cells can acquire MAPKi resistance and that their response to DUSP4 depletion remains unchanged despite changes in MITF levels during the acquisition of drug resistance." (PMID 35580987, 2022).